OCM (oncomodulin)
Description:
Has some calmodulin-like activity with respect to enzyme activation and growth regulation. Binds two calcium ions.
Synonyms: OM; OCM1; ONCM
Tractability: Antibody: the Human Protein Atlas places it where antibodies can reach.
Gene: Protein-coding gene on chromosome 7 (5,879,827 to 5,886,363, forward strand). Ensembl gene ENSG00000122543.
Subcellular location (Human Protein Atlas): Plasma membrane; Cytosol
Gene Ontology:
Molecular function: calcium ion binding; protein binding
Cellular component: cytoplasm
Genetic constraint (gnomAD): Loss-of-function variants: 18 observed, 13.34 expected, observed/expected ratio (o/e) 1.35, 90% interval 0.93 to 1.86. The upper end of that interval is the gene's LOEUF score, 1.86, which puts it in group 6 of 6, group 1 being the genes least tolerant of losing a copy. Missense variants: 140 observed, 137.35 expected, observed/expected ratio (o/e) 1.02, 90% interval 0.89 to 1.17. Synonymous variants: 48 observed, 50.52 expected, observed/expected ratio (o/e) 0.95, 90% interval 0.75 to 1.21.
Homologues: Orthologues: chimpanzee OCM (99% identical), dog OCM (97% identical), guinea pig Ocm (97% identical), macaque OCM (97% identical), rat Ocm (89% identical), mouse Ocm (88% identical), zebrafish pvalb5 (49% identical). Paralogues in human: OCM2 (98% identical), PVALB (51% identical).
Diseases named in the same sentence as OCM in open-access papers:
OCM is named in the same sentence as 20 diseases in open-access papers, as found by Europe PMC text mining. Sharing a sentence is not in itself a finding about the gene and the disease. The quoted sentences say what the papers report.
hearing loss (3 papers, 2021 to 2026). "Further, having a similar early progression of hearing loss across genetic strains argues that OCM possibly mediates sensitivity to ARHL." (PMID 34867279, 2021). "To date, oncomodulin (OCM), a small EF-hand Ca2+ binding protein (CaBP) belonging to the parvalbumin family of CaBPs, is the only mobile Ca2+ buffer that is associated with a hearing loss phenotype." (PMID 39507624, 2024).
ovarian carcinoma (3 papers, 2020 to 2023). A malignant neoplasm originating from the surface ovarian epithelium. "Initial observations showed associations between five SNPs of the OCM genes and the risk of ovarian cancer." (PMID 37628752, 2023). "We further observed that OCM promotes ovarian cancer cell migration and invasion (lower left), along with increased capacity to mediate angiogenesis (lower right)." (PMID 32071289, 2020). "To assess the prognostic capability of OCM genes in ovarian cancer, we evaluated whether OCM was preserved in healthy state." (PMID 36338962, 2022). "Since OCM genes were highly correlated in the diseased state, but not in healthy state, this module was considered as a prognostic module in ovarian cancer." (PMID 36338962, 2022).
hepatoma (1 paper, 2022). "One candidate is oncomodulin (Ocm), an EF-hand Ca2+ buffer protein, which was originally detected in rat hepatoma cells." (PMID 35131866, 2022).
tumor (12 papers, 2012 to 2025). "Conversely, the genes downregulated in the MYB-expressing epithelial clusters were predominantly tumor-suppressive transcriptional signatures, including OCM, IER2, JPH2, RYR3, MYH11and B3GALT1." (PMID 40950184, 2025). "Throughout the 1980s and early 1990s there were several studies aimed at evaluating OCM expression in various tumor types." (PMID 31649505, 2019). "Does OCM play a different role in tumor and cytotrophoblasts cells compared to roles of OCM in either hair cells or immune cells?" (PMID 31649505, 2019). "OCM is expressed in human tumor biopsies and solid tumors were generated in nude rats by injection of transformed cell lines, cell lines derived from human cancers, and extracts from human and rat tumors." (PMID 31649505, 2019). "Conflicting OCM expression in rodent and human primary tumor analyses may be why interest in this protein as a potential cancer marker waned." (PMID 31649505, 2019). "However in some cases, non-specific antibody staining sometimes made it appear that normal tissues were positive for anti-OCM reactive species, and not all human tumor cell lines test strongly for OCM as in rodent counterparts." (PMID 31649505, 2019).
cancer (7 papers, 2009 to 2023). A tumor composed of atypical neoplastic, often pleomorphic cells that invade other tissues. "The role of OCM gene polymorphisms in cancer patients has often been the subject of research." (PMID 37628752, 2023). "The initial discovery of OCM as an oncoprotein in cancer tissue and its similarity to calmodulin as a CaBP led to the term “oncomodulin”." (PMID 37538852, 2023). "Hair cells, notably OHCs, highly express another protein, which has also been used as a prognostic marker in cancer: oncomodulin (OCM)." (PMID 37538852, 2023). "Initially, the discovery of OCM in several types of mouse, rat, and human tumors made OCM attractive as a potential cancer marker." (PMID 31649505, 2019). "Oncomodulin is a small calcium-binding protein related to β-parvalbumin that was originally found in malignant neoplasms and placenta, and has been classified as an oncodevelopmental protein." (PMID 19320974, 2009). "Expression of OCM in tumors also led to questions about the non-cancer function of the protein." (PMID 31649505, 2019).
psychiatric disorder (1 paper, 2025). A disorder characterized by behavioral and/or psychological abnormalities, often accompanied by physical symptoms. "It is closely related to psychiatric disorders; however, its role as an oncomodulin is not well understood." (PMID 39403837, 2025).
OCM also shares sentences with these, for which no sentence is quoted: uveal melanoma (6 papers); cutaneous melanoma (3); melanoma (3); non-small cell lung carcinoma (2); ocular melanoma (2); breast carcinoma (1); colonic tumors (1); depression (1); glaucoma (1); infection (1); lung carcinoma (1); mesothelioma (1); pancreatic cancer (1); viral infection (1).